CD68 (CD68 molecule)
Diseases named in the same sentence as CD68 in open-access papers (continued):
Sharing a sentence is not in itself a finding about the gene and the disease.
endometriosis (18 papers, 2009 to 2025). The growth of functional endometrial tissue in anatomic sites outside the uterine body. "Intriguingly, there was a weakly positive correlation between the proportion of endometrial CD68+ macrophages and baseline serum E2 levels, indicating a potential association among E2, local immune profiles, and endometriosis (r = 0.251, P = 0.009)." (PMID 34531861, 2021). "Additionally, a slightly positive correlation between baseline E2 levels and endometrial CD68+ macrophages in women with a history of endometriosis indicated a potential association among hormones, immune cell responses, and endometriosis." (PMID 34531861, 2021). "Moreover, endometriosis-associated changes in the macrophage subtypes occurred only in the CD14+low/CD68+low subpopulation." (PMID 32572831, 2020). "In support of a role for macrophages in the pathophysiology of endometriosis, immunoreactive CD68, a pan-macrophage marker, was detected in a baboon endometriotic lesion." (PMID 37104033, 2023). "Flow cytometric analysis showed that the abundance of CD68+CD86+ cells was lower than that of CD68+CD163+ in endometriosis-related peritoneal cells." (PMID 36263059, 2022). "Macrophages lacking p38 underwent M2 polarization and were marked as CD45+F4/80+CD11b+CD206+, which is similar to the observation in peritoneal macrophages from endometriosis patients marked as CD68+CD206+." (PMID 36263059, 2022). "The endometrial CD68+ macrophage proportion in the mixed endometriosis subgroup was higher than that in the control group (2.8% versus 2.1%, P = 0.043)." (PMID 34531861, 2021). "According to an analysis of immune responses, significantly increased endometrial CD68+ macrophages were observed in women with a history of mixed endometriosis compared to the control group." (PMID 34531861, 2021). "The number of CD68-positive cells and micro-vessel density were found to be significantly decreased in the eutopic endometrium of women with endometriosis and adenomyosis in the GnRH agonist group when compared with that in the non-treated group." (PMID 33980258, 2021). "Endometriosis lesions from women are highly infiltrated by CD68+ macrophages that are present within the stroma of the tissue and can also be found in close proximity to glands." (PMID 32038499, 2020). "Increased matrix metalloproteinase-9 (MMP-9) co-localized with CD68+ macrophages in the endometrium of women with endometriosis is indicative of an increase in the number of macrophages implicated in tissue remodeling." (PMID 32038499, 2020). "GnRHa decreased the infiltrationof CD68-expressing cells in the endometrium ofwomen with endometriosis and adenomyosis." (PMID 29043703, 2018). "Mean CD68 (+) cell count in the endometriosis and control groups were 216.10±104.41 and 175.93±43.05, respectively." (PMID 24639773, 2013). "Several proinflammatory/vascular/hormonal changes such as increased expressions of cytokeratin, CD34, CD68+ macrophages, increased Ki67, and inactivation of tumor suppressor genes may trigger endometriosis progression and malignant transformation." (PMID 39768471, 2024). "CD68+ peritoneal macrophages (pMφ) co-express MST1 with low expression in endometriosis." (PMID 36263059, 2022). "Similar to the mouse, our data indicates that one pMΦ subpopulation, the CD14+low/CD68+low cells, behaves abnormally in women with endometriosis, which may contribute to an impaired immune response after the initial development of endometriosis lesions." (PMID 32572831, 2020). "To conclude, in this study, we have shown that changes in pMΦ polarization in endometriosis patients are limited to the CD14+low/CD68+low pMΦ subpopulation, and that these changes are coupled with increases in Th2 and Treg cells in a switch to a type 2 immune response." (PMID 32572831, 2020). "Additionally, we identify a mixed MΦ1/MΦ2 subtype that is only decreased in the CD14+low/CD68+low pMΦ subpopulation in endometriosis." (PMID 32572831, 2020).
endometriosis (continued). "The CD14+low/CD68+low subpopulation showed a higher proportion of MΦ1 cells (8.6 times, p = 0.0042 for controls and 5.35 times, p = 0.005 for endometriosis) and a lower proportion of MΦ2 cells (1.8 times, p < 0.0001 for both controls and 2.0 times, p < 0.0001 for endometriosis) (bottom)." (PMID 32572831, 2020). "Here, we have shown that endometriosis is associated with changes in macrophage activation, with a shift from a MΦ1 to a MΦ2 type of immune response in the CD14+low/CD68+low subpopulation, indicating some plasticity of the cells in the development of the disease." (PMID 32572831, 2020). "Therefore, we examined the distribution and abundance of the MΦ2a (CD80−/CD163+/CD206+) and MΦ2b (CD80−/CD163+/CD86+) subtypes in controls and endometriosis in the CD14+low/CD68+low and CD14+high/CD68+high subpopulations." (PMID 32572831, 2020). "Our study confirms and further extends the observations of these earlier studies, showing that the increase in the relative abundance of the MΦ2 subtype and the corresponding decrease of the MΦ1 subtype in endometriosis are limited to the CD14+low/CD68+low pMΦ subpopulation." (PMID 32572831, 2020). "In endometriosis lesions recovered at surgery from women during the secretory (progesterone-dominated) phase, we could detect macrophages (CD68) that coexpressed IGF-1 using dual immunofluorescence." (PMID 31291762, 2019). "We hypothesized that orally administered simvastatin in patients with endometriosis might reduce serum MCP-1, endometriosis-associated MCP-1, and cluster of differentiation-68 (CD68), a surface marker for macrophages, expression." (PMID 28950844, 2017). "In this study, we have identified the CD14+low/CD68+low pMΦ subpopulation as that that undergoes changes in MΦ polarization in endometriosis, but further characterization of this subpopulation will be required before such targeted therapies could be trialled as a treatment for the disease." (PMID 32572831, 2020). "In a subset of 32 patients (13 controls and 19 women with endometriosis), PF was fixed, processed and thinlayers were prepared and stained with Papanicolaou method and with immunocytochemistry using monoclonal antibodies against cytokeratin 7(CK 7), CK 8/18, Ber-Ep4, vimentin, calretinin and CD68." (PMID 19878540, 2009). "In ovarian endometriotic lesions, we observed significantly more CD68+ macrophages and DC-SIGN+ macrophages than in the normal endometrium and in the eutopic endometrium of endometriosis patients." (PMID 35260161, 2022). "We found an increased vascularity (CD34+) in the areas with abdominal endometriosis and CD3+−:T-lymphocytes, CD20+−:B-lymphocytes, CD68+:macrophages, and Tryptase+: mastocytes were abundant, especially in cases with adenomyosis as a marker of proinflammatory microenvironment." (PMID 35628423, 2022). "We first compared the relative abundance of MΦ1, MΦ1/MΦ2 and MΦ2 macrophages present in the CD14+low/CD68+low subpopulation in women with and without endometriosis." (PMID 32572831, 2020). "The expression level of CD14 and CD68 was correlated, with contour plots revealing distinct CD14+low/CD68+low and CD14+high/CD68+high subpopulations in both women with and without endometriosis (right)." (PMID 32572831, 2020). "We demonstrated that CD68 gene expression in endometriosis was not affected by simvastatin administration." (PMID 28950844, 2017). "Others factors, like estrogen receptor (ER) alpha, ERbeta, CD68, NCL-MACRO, and HAM56 and inflammatory cytokines IL-1beta, TNF-alpha, and IL-6, as well as pro-inflammatory transcription factor NF-κB are upregulated in macrophages from peritoneal fluid in patients with endometriosis." (PMID 32751735, 2020). "This was confirmed by cells in the CD14+high subpopulation showing a significantly higher CD68 mean fluorescence intensity (MFI) than cells in the CD14+low subpopulation for both women with and without endometriosis, indicating that CD14 and CD68 levels are highly correlated in pMΦ (bottom)." (PMID 32572831, 2020).
endometriosis (continued). "However, the relative abundance of this mixed MΦ1/MΦ2 subtype did not significantly differ between the CD14+low/CD68+low and CD14+high/CD68+high subpopulations of macrophages in either women with or without endometriosis (bottom)." (PMID 32572831, 2020).
metastatic tumors (18 papers, 2016 to 2026). "In this study, these groups were associated with different clinical outcomes, and CD68/CD163/CD209-immune hotspots predicted progression to metastatic disease and cancer-specific survival." (PMID 37190147, 2023). "In our cohort, CD68/CD163/CD209-immune hotspots predicted progression to metastatic disease and cancer-specific survival." (PMID 37190147, 2023). "CD68 positive cell density was higher in the metastatic tumor compared with primary sites, which indicated that more TAMs were infiltrated in the hepatic metastasis area." (PMID 34580284, 2021). "Interestingly, this study reported that the CD8/CD4 ratio and CD8/CD68 ratio were significantly reduced in metastatic tumors compared with the corresponding primary tumors, suggesting a tolerogenic and tumor-promoting microenvironment at the metastatic site." (PMID 33352665, 2020). "In addition, immunohistochemistry and multiplex immunofluorescent staining confirmed that the ratio of CD163/CD68-positive cells was significantly increased in the liver metastatic tumor (p = 0.0313), suggesting the crucial role of M2 macrophage infiltration in the pathogenesis of HPD." (PMID 39289546, 2024). "Furthermore, the density of HO-1+ cells in TINT increased with tumor aggressiveness, suggesting that fast-growing and metastatic tumors attract more HO-1+ macrophages (as well as CD68+ and CD163+ macrophages ) to the tumor-bearing organ than slow-growing and non-metastatic tumor variants." (PMID 27280718, 2016). "TAMs with double positivity for CD68 and CD163 are more likely to be found in lymph node metastatic tumors in the tumor microenvironment." (PMID 41256322, 2025). "Fifty-nine tumor samples from patients with pathologically confirmed squamous cell carcinoma of the larynx, stage I–IV non-metastatic disease, who were treated at the University Hospital of Split, were immunohistochemically stained for the expression of STING, cGAS, CD8, CD68, and CD163." (PMID 37444620, 2023). "One injection of MLL-EVs significantly increased macrophage infiltration (CD68) to the normal prostate tissue in vivo compared to G-EVs and PBS injected controls, suggesting that EVs from metastatic tumors could increase macrophage infiltration to the normal tissue surrounding the tumor." (PMID 27550147, 2016).
cervical carcinoma (17 papers, 2012 to 2025). A carcinoma arising from either the exocervical squamous epithelium or the endocervical glandular epithelium. "This was also observed in oropharyngeal squamous cell carcinomas and cervical carcinomas, where CD68+ macrophage infiltration was independently associated with tumor stage." (PMID 29541395, 2018). "Studies have shown that the density of CD68+TAM in cervical carcinoma tissue is higher than that in adjacent tissue and normal tissue." (PMID 34994088, 2022). "A total of three publications analyzed the high expression of CD68+ TAM in cervical cancer and paracarcinoma or normal tissue." (PMID 33928349, 2021). "At diagnosis, diverse immune cell types including CD20+ B cells, CD3+ T cells, CD56+ natural killer (NK) cells, and CD68+ macrophages were detected in different proportions of cervical carcinoma." (PMID 33087896, 2021). "In squamous cell carcinomas, recent studies found a positive correlation between CD68+ macrophages (both M1 and M2 phenotypes) and tumor progression in cervical cancers." (PMID 29541395, 2018). "However, CD68+CD163+ (double positive) macrophages were numerous in the TC from cervical cancer tissues and the increased densities of both markers were associated with poor prognosis." (PMID 33995627, 2021). "It showed that there was a significant difference between cervical cancer and paracarcinoma or normal tissue (OR = 12.03, 95% CI: 7.01–20.63, P<0.001), indicating that the density of CD68+ TAM in cervical cancer was much enhanced than that in paracarcinoma or normal tissue." (PMID 33928349, 2021). "Diverse immune cell types including CD20+ B cells, CD3+ T cells, CD56+ natural killer (NK) cells, and CD68+ macrophages and immune markers PD-L1 were detected in different proportions of cervical carcinoma, and these cellular and molecular indicators are typically associated with patient’ survival." (PMID 34458135, 2021). "CD3+ tumor infiltrating T cells (TILs), CD45RO+ TILs, CD4+ TILs, CD8+ TILs, FOXP3+ TILs (regulatory T cells, Tregs), CD68+ tumor associated macrophages (TAMs), CD163+ TAMs, and PD-L1+ tumor cells were immunostained in formalin-fixed paraffin-embedded (PPFE) tissues from 96 cervical cancer patients." (PMID 31616592, 2019). "H-score was used to analyze the expression of CD20, CD57, CD68 and CD163 in cervical cancer microarray." (PMID 37642715, 2023). "In this study, we showed for the first time that a high number of CD68/c-Maf -positive macrophages was correlated with prognosis in patients with LAD, similar to the findings of a previous report in cervical cancer." (PMID 37280312, 2023). "And six studies showed that the count of CD68 and CD163 TAMs in tumor stroma or nest was related to the occurrence and development of cervical cancer." (PMID 33928349, 2021). "The results of six articles showed that the high expression of CD68 and CD163 TAMs in tumor stroma or nest was correlated with the clinicopathological features of cervical cancer." (PMID 33928349, 2021). "In the included studies, the density of CD68+ and CD163+ TAM in cervical cancer was significantly enhanced than those in paracarcinoma or normal tissue." (PMID 33928349, 2021). "Our previous study suggests that tumor CD8+ T cells and macrophages (defined as CD68+ cells) infiltration underwent dynamic and heterogeneous changes during concurrent chemoradiotherapy (CCRT) in cervical cancer patients, which correlated with their short-term tumor response." (PMID 38654284, 2024). "However, as can be seen from the results of this meta-analysis, CD68+ TAM and CD163+ M2 TAM density in cervical cancer were significantly enhanced than those in paracarcinoma or normal tissue." (PMID 33928349, 2021). "The correlation coefficient between CD68+ M cells and CD163+ M2 cells was 0.8, also an evident positive correlation; moreover, CD68+CD163+ double positive M2 macrophages were also numerous in the TC from cervical cancer tissues." (PMID 33995627, 2021).
cervical carcinoma (continued). "Taken together, these results suggest that density patterns of different immune cell markers (namely CD3, CD4, CD8, CD20, CD57, CD68, and CD163) could be used to predict the prognosis of patients with cervical cancer and aid in evaluating the effectiveness of adjuvant chemoradiotherapy." (PMID 33995627, 2021).
Hepatic steatosis (17 papers, 2013 to 2026). Steatosis is a term used to denote lipid accumulation within hepatocytes. "Hepatic steatosis is usually accompanied by inflammation, thus we performed immunofluorescence (IF) staining of CD68+, and found the increased number of CD68+ cells in U‐NHP livers." (PMID 38816931, 2024). "Kupffer cells (KCs) are hepatic macrophages that play a pivotal role in the key steps of fatty liver progression to fibrosis, with CD68 as a surface marker." (PMID 37180164, 2023). "Knockout ACAA2 homolog MTP reduced fatty acid oxidation capacity in the liver, and increased hepatic steatosis and the expression of inflammatory marker CD68, accelerating the progression of NAFLD12." (PMID 37528093, 2023). "The overexpression of Sirtuin3 in MTP+/− mice significantly reduced the acetylation of MTP as compared with β-galactosidase controls and increased mitochondrial fatty acid oxidation and reduced hepatic steatosis, CD68 and serum ALT levels." (PMID 34446002, 2021). "Recently, research showed the CGA-attenuated MCP-1 and CD68 expressions in the hepatic steatosis model in mice." (PMID 31662982, 2019). "Overexpression of SIRT3 in MTP+/− mice significantly reduced the acetylation of MTP compared with β-galactosidase controls, increased mitochondrial FAO, and reduced hepatic steatosis, CD68, and serum ALT levels." (PMID 29581157, 2018). "Compared with WT, MTP+/− mice displayed reduced hepatic SIRT3 levels and reduced FAO, with increased hepatic steatosis and the inflammatory marker CD68." (PMID 29581157, 2018). "Oil Red O staining and IHC for F4/80 and CD68 revealed reduced liver steatosis and decreased macrophage activation and infiltration in HKO mice at both time points, emphasizing the protective role of SAMHD1 deficiency against hepatic lipid accumulation and inflammation." (PMID 41522335, 2026). "An immunohistochemical analysis of simple fatty liver and NASH revealed that the infiltration of CD68-positive macrophages, including Kupffer cells, was evident, even in the simple fatty liver stage of NAFLD." (PMID 32481552, 2020). "Histological liver analysis confirmed hepatic alteration in all treated groups, but it showed features of hepatic steatosis and macrophages infiltration worsened in DDE-treated rats, as confirmed by CD68 immunostaining." (PMID 31022254, 2019). "In this study, we showed that continuous administration of nicotine improved CDAA diet-induced hepatic steatosis and inflammation, and decreased the levels of hepatic TG, FFA, and the number of CD68-positive macrophages." (PMID 28662136, 2017). "Treatment with PRI-724, a β-catenin/CBP inhibitor, significantly ameliorates hepatic steatosis and fibrosis in MASLD mouse models, evidenced by increased hepatic Marco+Mmp9+Cd68+ KCs and reduced levels of ALT, Mac-2 bp, and fibrotic markers (collagen I/III, α-SMA)." (PMID 41394841, 2025). "Furthermore, Cr supplementation downregulates CD68 and myelo-peroxidase (MPO) protein expression, reduces levels of pro-inflammatory cytokines in serum, and increases the secretion of the anti-inflammatory cytokine in hepatic steatosis animal models." (PMID 38721033, 2024).